MGAT3 (beta-1,4-mannosyl-glycoprotein 4-beta-N-acetylglucosaminyltransferase)
Diseases named in the same sentence as MGAT3 in open-access papers (continued):
Sharing a sentence is not in itself a finding about the gene and the disease.
pancreatic carcinoma (4 papers, 2013 to 2020). "Among these, we successfully identified the functions of B3GNT3, GCNT3, FUT3 and MGAT3 in pancreatic cancer cells." (PMID 32203219, 2020). "After the multi-step validation, we identified B3GNT3, B4GALNT3, FUT3, FUT6, GCNT3 and MGAT3 as top-upregulated genes in aggressive pancreatic cancer cell lines Capan-1 and HPAF/CD18." (PMID 32203219, 2020). "The alterations in gene expression and glycome levels are also consistent with a previous report showing the increased degree of MGAT3 and MGAT5 activities in the tissues of pancreatic carcinoma patients." (PMID 32232009, 2020). "Altogether, we have systematically analysed the role of B3GNT3, MGAT3, FUT3 and GCNT3 in pancreatic cancer and illustrated the mechanism of GCNT3 in PC." (PMID 32203219, 2020).
colorectal cancer (3 papers, 2017 to 2025). A primary or metastatic malignant neoplasm that affects the colon or rectum. "Previous studies have shown that increasing MGAT3 expression can restore sensitivity to ICI therapy, offering a potential new strategy to overcome immune resistance in colorectal cancer." (PMID 40760673, 2025). "To address this aspect, we performed colocalization experiments of the enzymes involved in our predicted reactions, namely B4GalT1, MGAT3, and ST6Gal1, in kidney COS-7 cells and CaCo-2 colorectal cancer cells." (PMID 29133956, 2017).
glioblastoma (3 papers, 2016 to 2023). The most malignant astrocytic tumor (WHO grade IV). "Moreover, the TCGA HGSOC cohort showed significantly elevated MGAT3 expression compared to all remaining cancer types except for glioblastoma (p < 0.001)." (PMID 27429195, 2016).
Cognitive impairment (2 papers, 2015 to 2020). Abnormal cognition is characterized by deficits in thinking, reasoning, or remembering. "BACE1 has been reported to be highly modified with bisecting GlcNAc, and as previously discussed, in vivo studies in mice show that knock-out of the Mgat3-gene, encoding the GnT-III enzyme, improve cognitive impairment and reduce Aβ deposition." (PMID 33519371, 2020). "Moreover, cognitive impairment in hAPP/Mgat3+/+ mice as measured by the Y-maze test was significantly rescued in hAPP/Mgat3−/− mice (Fig4E)." (PMID 25592972, 2015).
Crohn disease (2 papers, 2013 to 2018). A gastrointestinal disorder characterized by chronic inflammation involving all layers of the intestinal wall, noncaseating granulomas affecting the intestinal wall and regional lymph nodes, and transmural fibrosis. "The association of the MGAT3 with both IgG N-glycosylation and Crohn’s disease suggests that N-glycans with bisecting GlcNAc could be involved in CD pathogenesis through functional effect on IgG antibody." (PMID 29991969, 2018). "Interestingly, ST6GAL1 has been previously associated with Type 2 diabetes, MGAT3 with Crohn's disease, primary biliary cirrhosis and cardiac arrest, and FUT8 with multiple sclerosis, blood glutamate levels and conduct disorder." (PMID 23382691, 2013). "We found significant differences in the methylation levels in the MGAT3 and BACH2 genes between both Crohn’s disease and ulcerative colitis when compared to HC." (PMID 29991969, 2018).
lung carcinoma (2 papers, 2018 to 2024). "In addition, a recent study showed that in lung cancer, MGAT3 was regulated by miR-188-5p, inhibiting the EMT process and cancer cell metastasis." (PMID 38521909, 2024).
prostate carcinoma (2 papers, 2019). A carcinoma that arises from epithelial cells of the prostate gland. "Moreover, we recently found that EtOH-induced Golgi disorganization in prostate cancer (PCa) cells is accompanied by mislocalization of the N-glycosylation enzyme, N-acetylglucosaminyltransferase-III (MGAT3), again implying its sensitivity to giantin." (PMID 31847122, 2019).
ulcerative colitis (2 papers, 2016 to 2018). An inflammatory bowel disease involving the mucosal surface of the large intestine and rectum. "Additionally, treatment with mesalamine (an anti-inflammatory drug used to treat ulcerative colitis) increases MGAT3 expression in mice intestinal polyps (which normally show a low expression of MGAT3)." (PMID 26539643, 2016). "Finally, we showed that CpG methylation in the promoter of the MGAT3 gene is altered in CD3+ T cells isolated from inflamed mucosa of patients with ulcerative colitis from a third smaller cohort, for which biopsies were available, suggesting a functional role of this glyco-gene in IBD pathogenesis." (PMID 29991969, 2018).
asthma (1 paper, 2024). "Second, we lacked sufficient sputum or bronchoalveolar lavage fluid (BALF) samples to detect differences in the expression of circ_0070934, miR-199a-5p, and MGAT3 to further illustrate their relevance to asthma." (PMID 38521909, 2024). "The objective of this investigation was to elucidate the functional dynamics of the circ_0070934/miR-199a-5p/Mannoside acetylglucosaminyltransferase 3 (MGAT3) axis in the development of asthma." (PMID 38521909, 2024). "And the expression of MGAT3 was reduced in sputum of asthma patients." (PMID 38521909, 2024). "Therefore, circ_0070934, miR-199a-5p and MGAT3 were of some significance in the diagnosis of asthma and may be used as potential biomarkers for asthma diagnosis." (PMID 38521909, 2024). "Mechanistically, circ_0070934 regulated the expression of MGAT3 gene by targeting miR-199a-5p as a ceRNA and affect the EMT process of bronchial epithelial cells, thus affecting the progression of asthma." (PMID 38521909, 2024).
chronic myelogenous leukemia (1 paper, 2024). "Our study highlights the critical role of MGAT3 in regulating erythroid differentiation associated with the ERK/mitogen-activated protein kinase signaling pathway, which may shed light on identifying new differentiation therapy in chronic myelogenous leukemia." (PMID 39571652, 2024).
Cirrhosis (1 paper, 2025). A chronic disorder of the liver in which liver tissue becomes scarred and is partially replaced by regenerative nodules and fibrotic tissue resulting in loss of liver function. "Additionally, MGAT3 activity in B cells, which produce IgA after differentiation into plasma cells, increases during liver fibrosis/cirrhosis." (PMID 39849179, 2025).
galactosaemia (1 paper, 2018). "Modification of branched N-glycans structures such as bisecting GlcNAc, β-1,6-GlcNAc and core fucose (α-1,6-fucose), the enzymatic products of MGAT3 and FUT6 genes, shown to be abnormal in galactosaemia, are highly associated with biological functions involving cell adhesion." (PMID 30231941, 2018).
gastric carcinoma (1 paper, 2015). A carcinoma that arises from epithelial cells of the stomach. "However, during gastric carcinoma formation, E-cadherin and integrins alter their glycosylation status by promoting MGAT3 expression during gastric carcinoma formation." (PMID 26132161, 2015).
head & neck squamous cell carcinoma (1 paper, 2016). "The MGAT3 expression varied among all TCGA datasets from being the lowest in head & neck squamous cell carcinoma to being the highest in HGSOC." (PMID 27429195, 2016).
IgA nephropathy (1 paper, 2024). "IgA N-glycans associations at the ST6GAL1, MGAT3, and ELL2 loci were also identified in QMDiab, with lead SNPs at the ST6GAL1 and ELL2 loci being coincident or in strong linkage disequilibrium (LD) with previously reported associations for IgA nephropathy and multiple myeloma risk, respectively." (PMID 39123268, 2024).
juvenile idiopathic arthritis (1 paper, 2023). Juvenile idiopathic arthritis (JIA) is the term used to describe a group of inflammatory articular disorders of unknown cause that begin before the age of 16 and last over 6 weeks. "A gene-set analysis indicated that IgG glycosylation (TAB1, MGAT3, and CACNA1I) and Response to methotrexate in juvenile idiopathic arthritis (CACNA1I and APOBEC3C) may engage common underlying genetic vulnerabilities." (PMID 37029179, 2023).
liver fibrosis (1 paper, 2025). "We identified specific bisect N-glycans biosynthesized by MGAT3, and some of the carrier proteins, associated with the progression of liver fibrosis in patients with MASLD." (PMID 39849179, 2025).
lymph node metastasis (1 paper, 2025). "Transcriptomic profiling revealed a molecular signature (ALDH1A3, CTXN1, MGAT3, and TMEM163) of occult lateral lymph node metastasis, exhibiting strong robustness (AUC = 0.857)." (PMID 40977710, 2025).
metastatic tumors (1 paper, 2020). "A significant reduction of the mRNA and protein levels of MGAT3 was detected in metastatic tumors as well as in the ascites compared to primary tumors." (PMID 32483464, 2020).
myelogenous leukemia (1 paper, 2014). "Overexpression of MGAT3 in HeLaS3 cells enhanced the epidermal growth factor (EGF) mediated cell signaling, and transfecting myelogenous leukemia cell line K562 with MGAT3 protected it from natural killer cytotoxicity and increased spleen colonization." (PMID 24516574, 2014).
ovarian tumors (1 paper, 2020). "In agreement with the results obtained in mice, a dramatic reduction of MGAT3 expression was detected in human metastatic ovarian tumors at the mRNA and protein levels." (PMID 32483464, 2020).
sarcopenia (1 paper, 2024). Progressive decline in muscle mass due to aging which results in decreased functional capacity of muscles. "Consistently across the three outcomes, RXRA, MDM1, RBL2, KCNJ2, and ADHFE1 were identified as risk factors, while NMB, TECPR2, MGAT3, ECHDC2, and GINM1 were identified as protective factors, all with potential as biomarkers for sarcopenia progression." (PMID 39409102, 2024).
schizophrenia (1 paper, 2012). A major psychotic disorder characterized by abnormalities in the perception or expression of reality. "(2010) described a comparable correlation between down-regulation of the MGAT3 gene encoding GlcNAc-T III and other genes on the transcriptional level and variations of the CSF glycome related to Schizophrenia." (PMID 22952606, 2012).
serous ovarian cancer (1 paper, 2016). "We analyzed MGAT3 expression and the corresponding DNA methylation in three additional serous ovarian cancer cell lines." (PMID 27429195, 2016). "The regulatory impact of DNA methylation on MGAT3 was further evaluated in 18 TCGA cancer types (n = 6118 samples) and the results indicate an improved overall survival in patients with reduced MGAT3 expression, thereby identifying long-term survivors of high-grade serous ovarian cancers (HGSOC)." (PMID 27429195, 2016). "The analysis of MGAT3 promoter DNA methylation was performed in normal human ovarian surface epithelial cell lines (HOSE6-3 and HOSE17-1) and two serous ovarian cancer cell lines (OVCAR3 and A2780), showing low and high MGAT3 expression, respectively." (PMID 27429195, 2016).
cancer (38 papers, 2009 to 2025). A tumor composed of atypical neoplastic, often pleomorphic cells that invade other tissues. "MGAT3 has been implicated in various cancers due to the important role it plays in reducing the hybrid and complex structures on N-glycans." (PMID 32203219, 2020). "Together these finding suggest the potential use for this antibody in diagnostic and therapeutic applications for cancers that have amplification of the Mgat3 gene." (PMID 30911061, 2019). "Interestingly, studies reported an association between reduced expression of MGAT3 and cancer metastasis 31-36." (PMID 32483464, 2020). "The changes in specific N-glycan structures according to the type of cancer observed here can be explained by the opposing roles of MGAT3 and MGAT5." (PMID 36890858, 2023). "In contrast, aberrant upregulation of MGAT3 and bisecting GlcNAc have also been identified in some cancer cells, promoting tumor malignancy." (PMID 34445285, 2021). "Based on this relationship, the present results, showing a higher cancer/normal ratio of MGAT3 expression compared with that of MGAT5 expression, are supportive evidence for the increase in bisecting GlcNAc in PDAC tissues." (PMID 32232009, 2020). "Targeting the interaction between miR-23a and Mgat3 would be a potential therapeutic approach to blocking cancer cell metastasis." (PMID 29743543, 2018). "The tree-based model selected a threshold (MGAT3 ≤ 1.67) in regards to survival separating all cancers (n = 3477) in low and high MGAT3 expression (p < 0.001)." (PMID 27429195, 2016). "Since this data indicates a tissue-specific regulation of MGAT3/bisecting GlcNAc expression in human cancers, the role of MGAT3/bisecting GlcNAc in cancer development or metastasis is very likely to differ within different types of human cancers." (PMID 27429195, 2016). "Based on the strong relationship observed between DNA methylation, MGAT3 gene and bisecting GlcNAc expression in various normal and cancer cell lines, we sought to reproduce our results in human cancer tissue samples." (PMID 27429195, 2016). "MGAT3 gene is also regulated by DNA methylation in other types of cancer and also during the process of EMT; in addition, GnT-IV genes (MGAT4A and 4B) were reported to be regulated by DNA methylation in pancreatic cancer." (PMID 27136596, 2016). "As a consequence, increased expression of MGAT3 deceased β1,6 GlcNAc branching and metastatic potential of cancer cells." (PMID 24516574, 2014). "In conclusion, an increasing number of studies have shown that MGAT3 could inhibit the EMT process in cancer cells, but its effect on EMT in airway epithelial cells remained understudied." (PMID 38521909, 2024). "In addition, MGAT3 has been considered a malignancy suppressor where its overexpression can inhibit metastatic profiles of cancer cells." (PMID 36890858, 2023). "Studies reported that the glycosyltransferase MGAT3 controls cancer proliferation, migration and metastasis although these effects may be beneficial or detrimental in a cell type-dependent manner 64-70." (PMID 32483464, 2020). "Mgat3-knockout mice showed reduced cancer growth in chemically induced liver cancer model." (PMID 31936666, 2020). "We analyzed the overall MGAT3 expression among all cancers ≤ (n = 12) in the TCGA PANCAN12 dataset to address the question whether MGAT3 expression is cancer-type specific." (PMID 27429195, 2016). "Moreover, the MGAT3 gene appeared among the ten highest ranked genes according to changes in expression and methylation levels in different cancers." (PMID 27073020, 2016). "However, the promoter of B4GALNT2 and ST3GAL6 seems to be hypermethylated in cancer in contrast to the MGAT3 promoter, which is hypomethylated." (PMID 27429195, 2016).
cancer (continued). "One mechanism reported to be responsible for inhibitory effects of MGAT3 on cancer metastasis is that addition of bisecting GlcNAc by MGAT3 hinders β1,6 GlcNAc branching formation catalyzed by MGAT5, since MGAT5 cannot utilize the bisected oligosaccharide as an acceptor substrate." (PMID 24516574, 2014). "Of interest, 3 GT families stood out in cancer cells after their interaction with platelets: MGAT2, MGAT3 and B3GNT which were significantly overexpressed by 343, 320 and 170%, respectively." (PMID 40096084, 2025). "We also measured the protein levels of three glycosyltransferases (MGAT3, MGAT4a, and MGAT5) previously reported to correlate with CD147 glycosylation in clinical samples such as cancer tissues." (PMID 35050217, 2021). "We observed a significant overexpression of Mgat5 glycogene as well as Mgat4a and Mgat3 in LGD, HGD, and carcinoma, when compared with inflamed tissue, suggesting an overall increase in complex N-glycosylation pathway along CAC development, which is in accordance with our human results." (PMID 40087977, 2025). "We expanded our study to epithelial cancer types other than HGSOC, demonstrating that DNA methylation and MGAT3 expression corroborates among almost all epithelial cancer types and has influence on disease outcome, independent of the cancer subtype." (PMID 27429195, 2016).
tumor (32 papers, 2004 to 2026). "For example, loss of Mgat3 in mice caused enhancement of the Ras pathway and promoted tumor progression in the mouse mammary tumor virus (MMTV)-polyoma middle T (PyMT) oncogene-induced mammary gland tumor model." (PMID 34445285, 2021). "According to previous studies, N-acetylglucosaminyltransferase III (GnT-III) which catalyzed β1, 4-bisecting- N-acetylglucosamine to N-glycan and encoded by Mgat3 gene has been found to act as suppressors in the tumor metastasis." (PMID 23977005, 2013). "Decreased levels of bisecting GlcNAc and MGAT3 were also observed in DOX-exposed tumor of MDA-MB-231, along with an increased P-gp expression." (PMID 39267774, 2024). "GnT-V and its products (β1,6-branched N-glycans) were positively correlated with tumor cell metastasis, whereas MGAT3, as an antagonist of GnT-V, suppressed metastasis." (PMID 29593568, 2018). "MGAT3 is considered a key glycosyltransferase in N-glycan biosynthetic pathways and was reported playing an important role in tumor progression." (PMID 24516574, 2014). "The impact of MGAT3 overexpression on tumor growth was subsequently evaluated." (PMID 40760673, 2025). "N-acetylglucosaminyltransferase III (GnT-III), encoded by the MGAT3 gene, is a crucial glycosyltransferase known for synthesizing a bisecting N-acetylglucosamine residue and has gained attention for its role in physiology and tumor biology." (PMID 39571652, 2024). "In the DOX-treated tumor-bearing nude mice, the introduction of bisecting GlcNAc by either overexpressing MGAT3 or forskolin treatment resulted in a significant reduction in tumor volume and weight, accompanied by an increase in cell apoptosis and a decrease in P-gp expression." (PMID 39267774, 2024). "For example, attachment of bisecting GlcNAc structures to growth factor receptors slowed tumor progression by inhibiting activation of growth factor signaling, and modification by MGAT3 of integrin N-glycosylation inhibited its ligand binding ability and consequent integrin-mediated signaling." (PMID 29593568, 2018). "Moreover, MGAT3−/− mice overexpressing the polyomavirus middle T (PyMT) oncogene under the control of the mouse mammary tumor virus (MMTV) promoter exhibited an increased tumor burden, increased migration and early metastasis to lung." (PMID 29593568, 2018). "The combined data indicates that effects of MGAT3 on tumor progression may vary with cell type." (PMID 24516574, 2014). "c-Kit–mediated cellular signaling and CD71 stability were significantly suppressed in MGAT3 KO cells compared to WT cells, suggesting that GnT-III expression profoundly impacts tumor biology, including malignancy and differentiation." (PMID 39571652, 2024). "For this reason, the role of N-acetylglucosaminyltransferase-III (GnT-III, MGAT3) to hinder terminal N-glycan processing by the addition of β1,4-GlcNAc residues (bisected N-glycan), has earned GnT-III a reputation as a tumor suppressor." (PMID 42258445, 2026). "MGAT3 modified N-glycosylation of epithelial growth factor receptor (EGFR) and integrin, and inhibited cell surface binding of EGFR/ integrin to galectin-3, resulting in their endocytosis, suppression of intracellular signaling, and consequent promotion of cell migration and tumor metastasis." (PMID 29593568, 2018). "In addition, our meta-analysis of the methylation/expression level of the MGAT3 gene in 81 HCC patients and corresponding adjacent non-tumour tissue showed that this gene is hypomethylated in tumour and has increased expression." (PMID 27073020, 2016).